DDX5 (DEAD-box helicase 5)
Diseases named in the same sentence as DDX5 in open-access papers (continued):
Sharing a sentence is not in itself a finding about the gene and the disease.
hypertensive nephropathy (1 paper, 2023). Kidney damage that results from chronically elevated blood pressure; complications include glomerular damage resulting in proteinuria and hematuria. "By upregulating the expression of miR-205 and miR-206 in MVs secreted by EPC, the transcriptional activity of DDX5 and the activation of caspase-3/9 can be inhibited, thereby promoting the growth of PRKs and protecting the injury caused by hypertensive nephropathy." (PMID 36845016, 2023).
in situ breast cancer (1 paper, 2019). "Nevertheless, lower expression of both DDX5 and DDX17 has been reported in in situ breast cancer, along with increased MacroH2A1.1/MacroH2A1.2 ratios." (PMID 31164793, 2019).
influenza (1 paper, 2025). An acute viral infection of the respiratory tract, occurring in isolated cases, in epidemics, or in pandemics; it is caused by serologically different strains of viruses (influenzaviruses) designated A, B, and C, has a 3-day incubation period, and usually lasts for 3 to 10 days. "DDX5 and DDX17 both influence viral replication of human immunodeficiency virus (HIV), HBV and influenza." (PMID 40257982, 2025). "DDX5 and DDX17 promote influenza, HIV-1 and Sindbis infection, and singularly have proviral or antiviral roles in other RNA or DNA virus infections." (PMID 40257982, 2025).
Insulin resistance (1 paper, 2025). Increased resistance towards insulin, that is, diminished effectiveness of insulin in reducing blood glucose levels. "DDX5 upregulated Sestrin3 (SEST3), a stress-induced protein involved in reducing intracellular reactive oxygen species levels and implicated in blood glucose regulation, insulin resistance, and lipid storage in obesity." (PMID 41333436, 2025).
intestinal cancer (1 paper, 2020). "Identification of DDX5 as a common upstream regulator of tissue-specific oncogenic molecules provides an excellent therapeutic target for treating intestinal cancers." (PMID 32817263, 2020).
ischemia (1 paper, 2025). A hypoperfusion of the BLOOD through an organ or tissue caused by a PATHOLOGIC CONSTRICTION or obstruction of its BLOOD VESSELS, or an absence of BLOOD CIRCULATION. "For example, circIGF1R promotes cardiac repair by interacting with DDX5 to enhance its stability and activate β-catenin signaling post-ischemia." (PMID 41049614, 2025).
lipodystrophy (1 paper, 2015). A congenital or acquired disorder characterized by abnormal loss or redistribution of the adipose tissue in the body. "In future studies it will be of interest to examine how the loss of Ddx5 affects lipid droplet biology given the increasing evidence of genes expressing lipid droplet associated proteins being implicated in metabolic diseases such as lipodystrophy." (PMID 26637310, 2015).
lymph node metastasis (1 paper, 2019). "Higher O‐GlcNAcylation and DDX5 expression were not correlated with age, gender, or tumour location (P > 0.05) but were significantly positively associated with lymph node metastasis, tumour size, and the American Joint Committee on Cancer (AJCC) status (P < 0.05)." (PMID 30484950, 2019).
malaria (1 paper, 2023). Malaria is a serious and sometimes fatal disease caused by a parasite that commonly infects a certain type of mosquito which feeds on humans. "Because the functional role in gene regulation of Pf-DDX5 in malaria parasites has not been reported, we used the Pf-DDX5 knock-sideways strategy to displace most of the nuclear Pf-DDX5." (PMID 36379669, 2023).
malignant peripheral nerve sheath tumor (1 paper, 2014). Malignant peripheral nerve sheath tumor (MPNST) is a rare and often aggressive soft tissue sarcoma occurring in a wide range of anatomical sites. "Significant association has been also reported between DDX5 rs1991401 (OP = 7.90×10−5) and malignant peripheral nerve sheath tumor." (PMID 24796549, 2014).
multiple sclerosis (1 paper, 2025). A progressive autoimmune disorder affecting the central nervous system resulting in demyelination. "Also, the loss of BIN1 parallels myelin loss in multiple sclerosis brain lesions neurodegeneration, and DDX5 is involved in MBP regulation." (PMID 40943121, 2025).
myeloproliferative neoplasm (1 paper, 2024). A clonal hematopoietic stem cell disorder, characterized by proliferation in the bone marrow of one or more of the myeloid (i.e., granulocytic, erythroid, megakaryocytic, and mast cell) lineages. "We previously found that DDX5 played an essential role in the signaling pathway of the tyrosine kinase Janus kinase 2 (JAK2) V617F mutant, which causes myeloproliferative neoplasms (MPN)." (PMID 38612503, 2024).
myotonic dystrophy (1 paper, 2018). An inherited progressive disorder affecting the muscles. "Overexpression of DDX5 also restores the skeletal muscle function in a mouse model of myotonic dystrophy." (PMID 29518074, 2018).
nasopharyngeal carcinoma (1 paper, 2025). A carcinoma arising from the nasopharyngeal epithelium. "In nasopharyngeal carcinoma (NPC), the same family of HMGB2, high mobility group box 1 (HMGB1), the direct target of dead box helicase 5 (DDX5), is upregulated by the NAT10-mediated ac4C modification of DDX5, which inhibits the T-cell immunity of CD4 + and CD8 + T cells and promotes NPC progression." (PMID 41316475, 2025).
osteoarthritis (1 paper, 2024). A noninflammatory degenerative joint disease occurring chiefly in older persons, characterized by degeneration of the articular cartilage, hypertrophy of bone at the margins and changes in the synovial membrane. "Targeted upregulation of DDX5 in mouse chondrocytes inhibits hyaline cartilage fibrosis and degradation via pre-mRNA splicing and G4 unwinding, a potential therapeutic strategy against osteoarthritis." (PMID 38760576, 2024).
osteoporosis (1 paper, 2022). A condition of reduced bone mass, with decreased cortical thickness and a decrease in the number and size of the trabeculae of cancellous bone (but normal chemical composition), resulting in increased fracture incidence. "DDX5 is differentially expressed in bone marrow microenvironment of osteoporosis patients." (PMID 35859791, 2022).
papillary thyroid carcinoma (1 paper, 2022). "PWRN2 sponges miR-325, to prevent miR-325 from targeting DDX5, thus promoting the progression of papillary thyroid carcinoma." (PMID 35992805, 2022).
Premature ovarian insufficiency (1 paper, 2024). Amenorrhea due to loss of ovarian function before the age of 40. "Cells expressing premature ovarian insufficiency-causative mutants of MCM8 with decreased interaction with DDX5 displayed increased R-loop levels." (PMID 38858601, 2024).
SARS-CoV infection (1 paper, 2024). "Moreover, specific members of this family, such as DDX-5, have been demonstrated to interact with SARS-CoV infection." (PMID 39066279, 2024).
stomach cancer (1 paper, 2023). "In our study, we also found that there is an upregulation of DDX5 expression in cancerous tissues compared to paraneoplastic tissues, and that high DDX5 expression is closely associated with the prognosis of patients with gastric tumours." (PMID 36996491, 2023). "Next, to assess the regulatory function of DDX5 in the migratory capacity of gastric tumour cell lines, DDX5 was transfected into AGS cells and 7901 cells using a DDX5 expression vector." (PMID 36996491, 2023).
thyroid (1 paper, 2025). "documented that LncSLC26A4‐AS1 inhibits thyroid metastasis by promoting the binding of DDX5 and the E3 ligase TRIM25." (PMID 40490947, 2025).
tongue cancer (1 paper, 2023). A malignant neoplasm affecting the tongue. "Elevated DDX5 expression in tongue cancer is associated with a more favorable prognosis for clinical patients." (PMID 38136426, 2023). "Enhanced DDX5 expression impedes proliferation, progression, and resistance to cisplatin in tongue cancer and is associated with a more favorable prognosis for clinical patients." (PMID 38136426, 2023). "Notably, the knockdown of MMP10 considerably curtailed the viability of DDX5-KD tongue cancer cells, suggesting MMP10 as a pivotal gene that counteracts the DDX5-associated inhibition of tongue cancer cell proliferation." (PMID 38136426, 2023). "Moreover, we found that the expression of DDX5 in tongue cancer is associated with immune cell infiltration in the tumor microenvironment." (PMID 38136426, 2023). "Moreover, DDX5 expression in tongue cancer is associated with immune cell infiltration in the tumor microenvironment." (PMID 38136426, 2023). "DDX5 downregulates the genes associated with tongue cancer progression." (PMID 38136426, 2023). "Furthermore, the expression of DDX5 in tongue cancer is associated with immune cell infiltration in the tumor microenvironment." (PMID 38136426, 2023). "Our analysis extended to evaluating and ranking the expression of DDX5 in individual cancer cells derived from the six tongue cancer tissues under study." (PMID 38136426, 2023). "Remarkably, our research reveals that DDX5 counteracts the expression of genes pivotal to tongue cancer progression, such as MMP10." (PMID 38136426, 2023). "Consistently, the result of tongue cancer xenograft mouse models showed that the overexpression of DDX5 significantly suppressed tumor growth and development." (PMID 38136426, 2023). "Our study establishes DDX5 as a valuable prognostic biomarker and an important tumor suppressor in tongue cancer." (PMID 38136426, 2023). "In this study, we demonstrate that DDX5 serves as a tumor suppressor in the specific context of tongue cancer, which is contrary to its documented oncogenic role in a vast array of cancers." (PMID 38136426, 2023). "The high expression of DDX5 in tongue cancer correlates with a better prognosis in clinical patients." (PMID 38136426, 2023). "Intriguingly, we discovered that the genes upregulated in DDX5-KD tongue cancer cells are chiefly involved in the positive regulation of cytokine production, the regulation of viral processes, and the negative regulation of innate immune response." (PMID 38136426, 2023). "The high expression of DDX5 in tongue cancer is correlated with a better prognosis in clinical patients." (PMID 38136426, 2023). "We found that DDX5 expression had a significant correlation with CD8+ T cell infiltration in the TME of tongue cancer tissues." (PMID 38136426, 2023). "Collectively, these results indicate that elevated DDX5 expression in tongue cancer potentially inhibits the infiltration of macrophages exhibiting pro-cancer activity." (PMID 38136426, 2023). "Remarkably, we found that tongue cancer cells with higher DDX5 expression demonstrated a higher sensitivity to chemotherapy." (PMID 38136426, 2023). "The knockdown of DDX5 accelerates, while its overexpression inhibits, tongue cancer proliferation, development, and resistance to cisplatin." (PMID 38136426, 2023). "We found that, in the context of tongue cancer treatment, tumors with high DDX5 expression exhibited partial to complete remission." (PMID 38136426, 2023). "The high expression of DDX5 is correlated with better prognosis for clinical tongue cancer patients." (PMID 38136426, 2023). "The knockdown of DDX5 promotes, while the overexpression of DDX5 inhibits, tongue cancer proliferation, development, and cisplatin resistance." (PMID 38136426, 2023). "We found that the knockdown of DDX5 significantly promoted tongue cancer xenograft tumor development in mouse models." (PMID 38136426, 2023).
tongue cancer (continued). "Contrary to its documented oncogenic role in a wide array of cancers, we herein demonstrate that DDX5 serves as a tumor suppressor in tongue cancer." (PMID 38136426, 2023). "In this study, we establish DDX5 as a valuable prognostic biomarker and an important tumor suppressor in tongue cancer." (PMID 38136426, 2023). "We further analyzed the expression of DDX5 in tongue cancer in three datasets (GSE193445, GSE164619, GSE30784)." (PMID 38136426, 2023). "To delineate the role of DDX5 in tongue cancer, we established tongue cancer cell lines with a stable knockdown of DDX5 (DDX5-KD)." (PMID 38136426, 2023). "However, our study delineates a contrasting role for DDX5, demonstrating its function as a tumor suppressor in tongue cancer." (PMID 38136426, 2023). "Conversely, a substantial downregulation of DDX5 was observed in cases of advanced tongue cancer." (PMID 38136426, 2023). "Mouse models were used to examine the effect of DDX5 overexpression on tongue cancer development." (PMID 38136426, 2023). "Our study shows that DDX5 acts as a tumor suppressor and could potentially serve as a valuable prognostic biomarker and therapeutic target in tongue cancer." (PMID 38136426, 2023). "In addition, we employed multi-immunofluorescence staining to examine the relationship between DDX5 expression and the infiltration of Macro_spp1 (M2 type) in clinical tongue cancer samples." (PMID 38136426, 2023). "Additionally, DDX5 expression in tongue cancer is correlated with the infiltration of CD8+T cells in the TME." (PMID 38136426, 2023). "In this study, we show that DDX5 functions as a tumor suppressor and may serve as a valuable prognostic biomarker in tongue cancer." (PMID 38136426, 2023). "In contrast, our study suggests that DDX5 plays a tumor-suppressive role in tongue cancer." (PMID 38136426, 2023). "Furthermore, utilizing multi-immunofluorescence staining, we analyzed the correlation between DDX5 expression and CD8+ T cell infiltration in clinical tongue cancer tissues." (PMID 38136426, 2023).
tonsillar cancers (1 paper, 2016). "Subsequent QRT-PCR measurement of Drosha, Dicer1, DDX5 and DGCR8 indicated a general overexpression of all four biogenesis components in tonsillar cancers." (PMID 26867589, 2016).
ulcerative colitis (1 paper, 2020). An inflammatory bowel disease involving the mucosal surface of the large intestine and rectum. "In humans, colonic tissues from ulcerative colitis (UC) patients have higher DDX5 expression than healthy controls." (PMID 32817263, 2020).
cancer (103 papers, 2009 to 2025). A tumor composed of atypical neoplastic, often pleomorphic cells that invade other tissues. "The downregulation of DDX5 by sorafenib, as observed in our studies, activates Wnt/β-catenin signaling leading to ferroptosis escape, a mechanism implicated in acquired cancer drug resistance." (PMID 39122708, 2024). "One of the genes with decreased chromatin accessibility in hypoxia was DDX5, encoding the RNA helicase, DDX5, which showed reduced expression in various cancer cell lines in hypoxic conditions, tumor xenografts, and in patient samples with hypoxic tumors." (PMID 37013907, 2023). "Initially, our finding that hypoxia leads to loss of DDX5 seemed contradictory to the finding that it is overexpressed in cancers." (PMID 37013907, 2023). "To date, PDAC and HCC are the only cancer types where low levels of DDX5 expression are reported to be associated with higher cancer malignancy and poor prognosis." (PMID 37596619, 2023). "Understanding the tertiary structure of Dbp2 is critical in the search for small molecule inhibitors of DDX5-associated cancers." (PMID 36894019, 2023). "This study is the first to investigate the association between the methylation levels of the DDX5 promoter and the incidence of cancer." (PMID 36313454, 2022). "These genes, such as ANXA1, SMC2, KIF23, and DDX5, are primarily associated with cancer cell proliferation, metastasis, and poor prognosis." (PMID 35184675, 2022). "The infiltration of cancer-associated fibroblasts was positively associated with the expression of DDX5 mRNA in CESC, CHOL, COAD, LIHC, OV, PAAD, and READ tumors but negatively correlated with TGCT tumors." (PMID 36313454, 2022). "The probable mechanisms underlying the roles of DDX5 in the occurrence and progression of cancer and clinical prognosis were additionally explored." (PMID 36313454, 2022). "The infiltration of CD8+ T cells, cancer-associated fibroblasts, and B cells was positively correlated with the expression of DDX5 mRNA." (PMID 36313454, 2022). "This study is the first to demonstrate a possible association between the expression of DDX5 mRNA and the infiltration of immune cells across all cancer types in TCGA." (PMID 36313454, 2022). "The results of enrichment analysis revealed the possible role of DDX5 protein by integrating information on the DDX5-binding proteins and the genes associated with DDX5 expression across the different cancer types." (PMID 36313454, 2022). "The findings revealed a strong association between DDX5 and its co-expressed genes in numerous cancer types." (PMID 36313454, 2022). "Kaplan-Meier analysis was subsequently performed for determining the association between the mRNA expression of DDX5 and the prognosis of patients across the various cancer types in TCGA." (PMID 36313454, 2022). "In most cancers, when DDX5/DDX17 expression levels are elevated, the risk of malignancy is higher, and clinical survival time is shorter." (PMID 35992805, 2022). "The results demonstrated that the mRNA expression of DDX5 was associated with the infiltration of numerous immune cells, including T-helper (Th), Tcm, Th2, and B cells in 38, 32, 29, and 8 cancer types, respectively." (PMID 36313454, 2022). "Similar to DDX3, the human Dbp2 ortholog DDX5 is connected to cancer predisposition, showing the importance of studying these G4 binding proteins at the molecular level." (PMID 34302476, 2021). "Noncanonical repressor DEAD-box RNA helicases (DDXs), such as DDX3X and DDX5, are also associated with the loss of E-cadherin in cancers, but DDX3X prefers to bind distal region of the E-cadherin promoter." (PMID 33608512, 2021). "Mutation and overexpression of DDX5 are found in human cancers, and its overexpression predicts advanced clinical stage and poor survival in colorectal cancer (CRC) patients." (PMID 32817263, 2020).